TLR4 (toll like receptor 4)
Diseases named in the same sentence as TLR4 in open-access papers (continued):
Sharing a sentence is not in itself a finding about the gene and the disease.
rheumatoid arthritis (continued). "For example, the combined application of mangiferin and cinnamic acid has exhibited the capacity to impede TLR4/NLRP3-activated pyroptosis, consequently alleviating rheumatoid arthritis." (PMID 37766966, 2023). "For example, the expression of miR-20a-5p was also downregulated by stimulation of toll-like receptor 4 (TLR4) and TLR2 ligands in rheumatoid arthritis fibroblast-like synoviocytes." (PMID 36634655, 2023). "Interestingly, paracrine ENO1 tends to activate the CD14-dependent TLR4 pathway via functionally binding with TLR4 on monocytes in rheumatoid arthritis (RA)." (PMID 36614179, 2023). "In rheumatoid arthritis, ENO-1 can be reattached to the cell surface of monocytes, which induces the CD14-dependent TLR4 signaling to stimulate their pro-inflammatory state." (PMID 38618493, 2023). "In autoimmune diseases characterized by TH22-/TH17-dominated immune responses, such as rheumatoid arthritis and Arthus reactions, the expression of TLR2, TLR4, and TLR5 is upregulated." (PMID 37760825, 2023). "Interestingly, paracrine ENO1 tends to activate the CD14-dependent TLR4 pathway via functionally binding with TLR4 on monocytes by a dual mechanism, initially pro-inflammatory and later anti-inflammatory, in rheumatoid arthritis (RA)." (PMID 36614179, 2023). "Resatorvid (TAK-242) is a newly developed, highly selective Toll-like receptor 4 (TLR4) antagonist that is effective for treating pulmonary inflammation, rheumatoid arthritis, and acute kidney damage." (PMID 36891156, 2023). "Toll-like receptor (TLR)-4 and TLR9 are known to play important roles in the immune system, and several studies have shown their association with the development of rheumatoid arthritis (RA) and regulation of tumor necrosis factor alpha (TNF-α)." (PMID 34635730, 2021). "LY96, also known as MD2, encodes a protein which often is a coreceptor with TLR4 forming the TLR4/MD2 complex and has previously been found to be upregulated in patients with rheumatoid arthritis." (PMID 34177888, 2021). "This study investigated whether microRNA-146a (miR-146a) mediating TLR4/NF-κB pathway affected proliferation and inflammatory responses of rheumatoid arthritis fibroblast-like synoviocytes from 12 RA patients (RA-FLSs)." (PMID 29844864, 2018). "Our results show that rheumatoid arthritis synovial fibroblasts (RASF) express a series of TLRs, including TLR2, TLR3, TLR4, and TLR9, with the predominant expression of TLR3." (PMID 24936783, 2014). "Anti-TLR4 antibodies are now being tested in phase II studies for the treatment of rheumatoid arthritis, while the TLR4 inhibitor JKB-121 is being tested for the treatment of nonalcoholic steatohepatitis." (PMID 36674680, 2023). "Although the role of TLR4 in SLE pathogenesis was well-defined in C57BL/6(lpr/lpr)-TLR4-deficient SLE model, TLR4 antibodies in a phase II clinical trial did not improve disease parameters of rheumatoid arthritis." (PMID 34721432, 2021). "We observed similar reductions of monocyte TLR-4 but not neutrophil TLR-4 in our recent HIIT study in rheumatoid arthritis (RA) patients." (PMID 32431698, 2020). "On the other hand, in agreement with the current study, paeonol decreased the TLR4/NF-κB/TNF-α/IL-6 inflammatory signaling pathway in lipopolysaccharide-induced acute lung injury and IL-1β-induced human fibroblast-like synoviocyte rheumatoid arthritis." (PMID 32104151, 2020). "Also, HMGB-1 is a mediator of inflammation, as a ligand of TLR2, TLR4, and RAGE, that can promote ECM degradation and activate cell autophagy, and it has been involved in various autoimmune diseases (e.g. rheumatoid arthritis)." (PMID 41225346, 2025). "While LPS levels and mRNA expression of TLR-4 were unchanged in AIA rats compared to controls, sCD14 levels were increased at all phases of arthritis, but they did not correlate with zonulin levels in AIA rats, contrary to what was observed in patients with rheumatoid arthritis." (PMID 37280714, 2023).
rheumatoid arthritis (continued). "There is strong evidence that synovial macrophages and chondrocytes express TLR2 and TLR4, while TLR4 senses more DAMPs than TLR2 in both OA and rheumatoid arthritis (RA)." (PMID 36032081, 2022). "On this topic, an increasing number of studies have emphasized the involvement of TLR4 and TLR3 in the development of arthritic conditions such as rheumatoid arthritis (RA) and osteoarthritis." (PMID 31028244, 2019). "The activated TLR4 by using endogenous ligands induces pro-inflammatory cytokine and chemokine production in both human synovial fibroblasts and peripheral blood mononuclear cells (PBMC) from rheumatoid arthritis patients leading to cartilage inflammation and degeneration." (PMID 30877182, 2019). "Increased expression of toll-like receptor 4 (TLR4) and its endogenous ligands, is characteristic of rheumatoid arthritis (RA) synovitis." (PMID 27716430, 2016). "Roelofs and colleagues analyzed the involvement of HSPB8 in the pathogenesis of rheumatoid arthritis (RA), showing that HSPB8 could induce monocyte-derived dendritic cell maturation and cytokine production in a TLR4-dependant way." (PMID 33562660, 2021). "Indeed, cPIP2 showed better inhibitory profile on TLR4 (IC50 25 μM) and was further tested in vivo in rheumatoid arthritis (RA) mice model." (PMID 32765484, 2020). "Apart from Gram-negative infections, the role of TLR4 has been established also in a number of diseases with sterile inflammation (e.g. atherosclerosis, rheumatoid arthritis (RA))." (PMID 26082317, 2013). "In rheumatoid arthritis patients, CD16+ monocytes expressed higher TLR2 than CD16− monocytes while no TLR4 expression level difference between the two monocyte subsets." (PMID 38660059, 2024). "Indeed, the increased TLR4 expression on CD8 + T cells has been found in patients with Rheumatoid Arthritis (RA) and responded to LPS to produce inflammatory cytokines; these CD8 + T cells contributed to inflammation and RA disease pathogenesis." (PMID 37138358, 2023). "Another possibility is that in the pathogenesis of rheumatoid arthritis, CXCL10 acts on CXCR3 rather than TLR4 on macrophages or T lymphocytes to activate ERK, thereby increasing the ability of macrophages or T lymphocytes to migrate." (PMID 37048082, 2023). "Recently, CD8+ T cells from a specific cohort of rheumatoid arthritis (RA) patients, unlike naive healthy donors and Systemic Lupus Erythematosus (SLE) patients, have been shown to express elevated surface TLR4 expression and also found to respond upon LPS treatment." (PMID 29740052, 2018).
Cerebral ischemia (168 papers, 2010 to 2026). Restriction of arterial blood supply to the brain associated with insufficient oxygenation to support the metabolic requirements of the tissue. "In the context of cerebral ischemia/reperfusion injury, TLR4 has been implicated in the inflammatory response." (PMID 39376599, 2024). "The anti-inflammatory and neuroprotective activities of phthalide after brain ischemia are probably associated with the inhibition of damage-associated molecular pattern (DAMP)/Toll-like receptor 4 (TLR4) pathway." (PMID 38992073, 2024). "TLR4 deficiency has been shown to regulate the polarization of microglia toward the M2 phenotype, improving neurological function following cerebral ischemia and traumatic brain injury." (PMID 37361996, 2023). "The markers of tissue damage caused by persistent cerebral ischemia and hypoxia are related to the expression of Toll-like receptor 4 (TLR-4) on the membrane of microglia." (PMID 38274227, 2023). "Our previous study found that the expression level of TLR4 was associated with epileptic seizures in rats after transient hyperglycemia and global cerebral ischemia." (PMID 36619717, 2022). "The activation of microglia via TLR-4 induces amplification of neuronal cell loss and axonal damage after cerebral ischemia." (PMID 29054968, 2017). "Our previous study demonstrated that the protective effect of ligustilide (LIG) against cerebral ischemia was associated with inhibition of neuroinflammatory response and Prx/TLR4 signaling in rats." (PMID 27716839, 2016). "For example, TLR4-deficient mice are protected against the inflammatory response following cerebral ischemia." (PMID 26597908, 2015). "There is usually no viral or bacterial infection in I/R models; recent research supports the notion that upregulated expression of TLR4 is implicated in activation of microglia in cerebral ischemia models." (PMID 24751148, 2014). "A variety of means have been used to demonstrated the effectiveness of inhibiting the expression of TLR2 and TLR4 and their downstream signaling pathways on protecting brain injury caused by cerebral ischemia and reperfusion." (PMID 23864765, 2013). "TLRs, especially TLR4, are involved in the inflammatory responses and neuronal damage associated with cerebral ischemia." (PMID 23414417, 2013). "By contrast, accumulating experimental evidences suggested that TLR2 and TLR4 play crucial roles in modulating inflammatory response caused by cerebral ischemia and reperfusion via linking to their endogenous ligands, respectively." (PMID 23864765, 2013). "It is intriguing that despite that there are several studies demonstrating neuroprotection in TLR2 and TLR4-deficient animals following cerebral ischemia, KO of the gene for the downstream adaptor molecule, MyD88, does not provide protection." (PMID 23097717, 2012). "Our data indicate that the IR-induced activation of NF-κB was attenuated in the Tlr4 KO animals, which is consistent with previous studies of Tlr4-deficient animals challenged with brain ischemia." (PMID 21031135, 2010). "Moreover, the brain damage and neuronal defects of TLR2- and TLR4-knockout mice were reduced after cerebral ischemia caused by MCAO." (PMID 33384585, 2020). "In conclusion, XMZS exerts neuroprotective effects against cerebral ischemia-reperfusion injury by modulating the TLR4/MYD88/NF-κB pathway, thereby attenuating microglia-mediated neuroinflammation." (PMID 42005317, 2026). "Cerebral ischemia can up-regulate TLR4 expression, leading to translocation of NF‐κB to the nucleus, which participates in the transcription of inflammatory factors." (PMID 40289983, 2025). "In summary, this study revealed that SB can protect against cerebral ischemia–reperfusion injury by controlling microglia polarization and microbiome-gut-brain axis to inhibit brain inflammation via the TLR4/MyD88/NF-κB pathway." (PMID 39962509, 2025).
Cerebral ischemia (continued). "The TLR4/IL-1β/NF-кβ signaling pathway has been reported to play a role in various CNS conditions, such as cerebral ischemia and traumatic brain injury." (PMID 40153412, 2025). "Restatorvid (TAK-242), another TLR4-targeted inhibitor, significantly reduced the infarct size and edema degree after cerebral ischemia and hypoxia in rats in an in vivo study." (PMID 40900923, 2025). "Evobrutinib treatment improves neurological function of mice with cerebral ischemia, and alleviates neuroinflammation by inhibiting M1 microglia polarization through TLR4/Myd88/NF-κB pathway." (PMID 40263985, 2025). "Among the various TLRs, TLR4 has been extensively studied and is notably activated after cerebral ischemia." (PMID 40791737, 2025). "Toll-like receptor 4 (TLR4) in microglia not only plays key role in inflammatory response resulted by cerebral ischemia, but also appears to be involved in changes of microglial morphology." (PMID 40289983, 2025). "EVs regulate IKBKG through miR-125a-5p to inhibit the TLR4/NF-κB signaling pathway and exert neuroprotective effects against cerebral ischemia, emphasizing the critical role of miR-125a-5p in neuroinflammation and neuronal death after CIRI." (PMID 40585973, 2025). "During cerebral ischemia–reperfusion, these DAMPs activate pattern recognition receptors—such as Toll-like receptor 4 (TLR4) and the NLRP3 inflammasome—in immune cells, thereby initiating a robust inflammatory response that exacerbates brain injury." (PMID 41614830, 2025). "In the early stage of cerebral ischemia, damaged neurons emit DAMPs that induce Toll-like Receptor 4 (TLR4) on microglia in the early stages of cerebral ischemia, activating these cells to create inflammatory cytokines through the NF-κB pathway." (PMID 38808718, 2024). "In fact, such TLR4‐mediated dysregulation of macrophage polarization has been described in liver cancer, focal cerebral ischemia–reperfusion injury and spinal cord injury." (PMID 39123292, 2024). "In supporting that, in a rat model of cerebral ischemia PCSK9 inhibition reversed the release of inflammatory cytokines induced by Toll-like receptor 4 (TLR4) and NF-κB activation." (PMID 39769398, 2024). "Meanwhile, TAK-242, a small-molecule compound that selectively inhibits TLR4 signaling, is neuroprotective in cerebral ischemia or intracerebral hemorrhage." (PMID 37528888, 2023). "In this study, we used bioinformatics to identify and validate the differential expression of three target genes of miR-202-3p, Ptgs2, Tlr4, and Ccr2, in the cerebral ischemia penumbra of mice." (PMID 37563282, 2023). "Several evidences suggest that excess inflammation from the brain HMGB1/TLR4 axis activation is strongly contributes to traumatic brain injury and cerebral ischemia reperfusion injury." (PMID 37132060, 2023). "Through the inhibition of the TLR4/NF-κB signaling pathway, meisoindigo effectively reduced cerebral ischemia injury by preventing NLRP3 inflammasome activation and the polarization of microglia M1." (PMID 38273974, 2023). "In conclusion, engeletin strongly prevents focal cerebral ischemia via suppression of the HMGB1/TLR4/NF‐κB inflammatory network." (PMID 37132060, 2023). "Baicalein was also reported to attenuate cerebral ischemia/reperfusion injury via inhibiting toll-like receptor 4 (TLR4) signaling." (PMID 37041597, 2023). "Stimulation of the vagus nerve during the acute stage of cerebral ischemia can inhibit M1-type polarization and promote M2-type polarization by blocking the TLR4/MyD88/NF-κB signaling pathway, leading to improved outcomes in ischemic stroke." (PMID 37361996, 2023). "Research has indicated that tanshinone IIA has the potential to modulate the TLR4/NF-κB p65 signaling pathway, enhancing oxidative stress levels to address hypoxic/ischemic encephalopathy." (PMID 37766966, 2023).
Cerebral ischemia (continued). "Our findings suggested that ATF3 repressed neuronal apoptosis and microglia activation caused by cerebral ischemia via targeting CCL2 and mediating the TLR4/NF‐κB signaling." (PMID 35263513, 2022). "Following cerebral ischemia, TLR4 gene expression is upregulated in neurons, along with an increase in inflammatory cytokines." (PMID 35510663, 2022). "It is suggested that TLR4/NF-κB signaling pathway ameliorates neural defects, cerebral infarction, and neuropathological changes in cerebral ischemia-reperfusion rats." (PMID 35463081, 2022). "The levels of TLR-4 mRNA increased in neurons after 1 h of cerebral ischemia, which was accompanied by a high level of multiple inflammatory cytokines." (PMID 35454994, 2022). "A recent study describes a novel mechanism by which D-carvone protects against cerebral ischemia/reperfusion-induced inflammatory response by suppressing the TLR4/NLRP3 cascade." (PMID 35625467, 2022). "The results demonstrated that ATF3 protein was significantly reduced and CCL2 protein was significantly increased in rats with cerebral ischemia, while TLR4/NF‐κB signaling pathway was significantly activated in MCAO rats." (PMID 35263513, 2022). "Our real-time PCR and immunofluorescence results demonstrated that the propofol treatment decreased the expression level of IL-6 mRNA and the number of TLR4-expressing microglia after cerebral ischemia." (PMID 36117859, 2022). "Either propofol (10 mg/kg) or vehicle was intravenously injected 10 min prior to the induction of brain ischemia in wild-type and TLR4 knockout mice." (PMID 36117859, 2022). "In neural stem cells, circRNA TTC3 sponges miR-372-3p to regulate TLR4 expression and prevent cerebral ischemia reperfusion injury." (PMID 34483886, 2021). "In vivo, Radix Ginseng is also reported to down-regulate the TLR4 expressions in disease-like animal models like cerebral Ischemia rats." (PMID 33790789, 2021). "Lactoferrin can inhibit TLR4-related pathways triggered by hypoxia–reoxygenation and ischemia-reperfusion, suggesting that lactoferrin can be used as a dietary intervention for cerebral ischemia." (PMID 35008558, 2021). "Studies have revealed that some substances that are released from the damaged cells, blood vessels, and extracellular matrices during cerebral ischemia would activate the Toll-like receptor 4 (TLR4)-mediated downstream signaling pathway." (PMID 34712659, 2021). "Numerous evidence has revealed that the TLR4 and TLR4-mediated MyD88-NF-κB signaling pathway play an important role in the regulation of the inflammatory reaction in a cerebral ischemia injury." (PMID 34712659, 2021). "After cerebral ischemia, TLR4 recognizes the endogenous substances released from brain tissue such as heat shock protein, fibrinogen, hyaluronic acid, heparan sulfate, etc., and finally activates NF-κB." (PMID 34712659, 2021). "Experimental and clinical studies have demonstrated the role of DAMPs (e.g., HMGB1 and Prxs) in TLR4-activated neuroinflammation after brain ischemia and hemorrhage." (PMID 34162400, 2021). "Our current results showing TLR4 signaling in penumbral astrocytes, in both acute and chronic focal cerebral ischemia, suggest a possible biphasic role for TLR4 signaling in cerebral ischemia." (PMID 32148958, 2020). "Other authors have suggested the role of either miR-182-5p in the neuroprotective effect of cerebral ischemia-reperfusion injury via regulation by TLR4 or miR-124 and miR-146a in reversing neuropathic pain through the TLR4 receptor." (PMID 32780740, 2020). "Cerebral ischemia/reperfusion activates the TLR4-mediated MyD88-dependent pathway and upregulates NF-κB." (PMID 32479555, 2020). "Electroacupuncture alleviates cerebral inflammation in cerebral ischemia/reperfusion injury through the TLR4/NF-κB pathway, which is accompanied with the suppressed secretion of the inflammatory cytokines TNF-α, IL-1β and IL-6." (PMID 32479555, 2020).